LEPR (leptin receptor)
Diseases named in the same sentence as LEPR in open-access papers (continued):
Sharing a sentence is not in itself a finding about the gene and the disease.
breast cancer (continued). "Lately, the role of leptin and leptin receptor in breast cancer cells has shed light on the role of the adipose environment in breast cancer." (PMID 30823902, 2019). "A positive association between leptin expression, LEPR, aromatase and MAPK and STAT3 activation has been suggested using tissue samples of patients with estrogen receptor positive breast cancer." (PMID 31380268, 2019). "A bidirectional communication between LEPR and ERα was suggested by the statistically significant correlation between the expression of both receptors in breast cancer cells lines and ex vivo studies." (PMID 31380268, 2019). "Leptin and the long form of leptin receptor (LEPR) are enriched in breast cancer tissues and promote cell proliferation, migration, and angiogenesis." (PMID 31324052, 2019). "Overall, our results identify for the first time leptin/leptin receptor/Hsp90 axis as an important regulator of exosome generation in mammary carcinoma cells." (PMID 31336913, 2019). "Over-expression of both LEP and LEPR in CRC, along with similar findings in our previous studies with breast carcinoma and related works of other authors suggest strong association of LEP/LEPR system with carcinogenesis." (PMID 31592340, 2019). "Egyptian patients with breast cancer frequently present the AA genotype of LEP G2548A compared to healthy women, while the LEPR Q223R polymorphism is associated with the development of breast cancer." (PMID 30404206, 2018). "Several researchers have also demonstrated reduced leptin and leptin receptor gene expression in breast cancer cell lines after treatment with curcumin." (PMID 28930270, 2017). "Leptin receptor over expression has been observed in breast cancer compared to normal mammary epithelium." (PMID 28930270, 2017). "High leptin receptor mRNA expression in breast cancer tissue was also established to predict poor prognosis in patients with high serum leptin levels." (PMID 27042159, 2016). "It will be of particular importance to determine the role of hyperglycosylated forms of leptin receptor in breast cancer progression." (PMID 24260287, 2013). "The association between polymorphism of obesity-related genes (LEP, LEPR and PON1) and breast cancer risk has been investigated." (PMID 23826274, 2013). "Inconsistent with the results of these studies, obese Zucker rats, which have defective leptin receptor, developed more mammary tumors than lean Zucker rats after exposure to the carcinogen, 7,12-dimethylbenzanthracene." (PMID 21338489, 2011). "Leptin and leptin receptor are involved in the development of normal mammary glands and in the progression of breast cancer." (PMID 21834963, 2011). "In breast cancer cell lines and in human primary breast carcinoma leptin receptor has been demonstrated to occur in combination with leptin." (PMID 20030801, 2009). "In breast cancer tissue, it was shown that leptin and leptin receptor are both expressed and that they act to favour cancer proliferation and metastasis." (PMID 16504019, 2006). "In the present study, we analysed LEP (-2548) G/A and LEPR Q223R genotypes in a series of breast cancer cases and normal controls." (PMID 16504019, 2006). "The LEP (-2548) G/A and LEPR Q223R Genotype distributions in Control Subjects and in Patients with Breast Carcinoma." (PMID 16504019, 2006). "We used the polymerase chain reaction and restriction enzyme digestion to characterize the variation of the LEP and LEPR genes in 308 unrelated Tunisian patients with breast carcinoma and 222 healthy control subjects." (PMID 16504019, 2006). "Both leptin and the leptin receptor are overexpressed in primary breast cancer tumors and lymph node metastases, suggesting that this signaling may contribute to cancer progression." (PMID 39609706, 2024). "Studies have described that leptin receptors (LEPR) exist in breast cancer patients." (PMID 37496015, 2023).
breast cancer (continued). "By contrast, a recent meta-analysis by Sayad and coworkers did not support the association of LEP gene rs7799039 and LEPR gene rs1137100 with breast cancer." (PMID 37274250, 2023). "Moreover, Kaplan–Meier survival analysis correlated leptin receptor expression with reduced overall survival in breast carcinoma patients, especially in basal-like cancer subtypes." (PMID 37509120, 2023). "Similarly, LEPR expression was positively correlated with tumor size and ER expression in breast cancer." (PMID 35223490, 2022). "The primary aim of this retrospective study was to investigate the correlation between the immunohistochemical expression of Ob-R (leptin receptor) with pCR (pathological complete response) in early breast cancer patients receiving neoadjuvant systemic treatment (NST)." (PMID 34210055, 2021). "It was also shown that the leptin receptor was expressed in breast cancer cells predominantly, relative to normal cells, which correlates with larger tumor size, lymph node and distant metastases, a shorter time free from recurrence of the disease, and a greater degree of disease severity." (PMID 33864589, 2021). "Studied polymorphisms of the LEP and LEPR genes do not increase breast cancer risk in the population of Polish women." (PMID 33864589, 2021). "Studies in animal models using mice with genetically obese leptin-deficient Lep ob/ob or leptin receptor–deficient Ob-R db/db did not detect mammary tumors in either case, indicating that an intact leptin axis is essential for these tumors to develop." (PMID 34868066, 2021). "Therefore, the relationship between LEP and LEPR gene polymorphisms and expression of ER, PR, and HER2 receptors in women with breast cancer was evaluated." (PMID 33864589, 2021). "Moreover, LEPR is expressed at higher levels in many tumour tissues than in normal tissues, including oesophageal cancer, colon cancer, breast cancer and gastric cancer cells." (PMID 33397392, 2021). "In addition, tamoxifen was found to increase the expression of leptin receptor in breast cancer cell lines, leading to the decrease of drug sensitivity in inhibiting cell proliferation." (PMID 33799880, 2021). "Furthermore, the data obtained emphasizes the possibility of blocking the leptin/leptin receptor axis, as an adjuvant therapy in cats with luminal B and triple-negative mammary carcinoma subtypes, as reported for breast cancer patients." (PMID 33644151, 2021). "An immunohistochemical analysis of bone metastatic tissue of breast cancer further showed that the leptin receptor was prevalently expressed in the cytosol and the nuclei of metastatic cells, whereas leptin was detected in both metastatic cells and stromal cells." (PMID 33799880, 2021). "Dysregulation of the leptin/leptin receptor has been suggested to participate in the development of a large variety of malignancies, including breast cancer, pancreatic cancer, thyroid cancer, endometrial cancer, and gastrointestinal cancer, predominantly through the JAK/STAT pathway." (PMID 34156978, 2021). "The molecular mechanisms underlying the association between increased adiposity and aggressive breast cancer phenotypes remain unclear, but likely involve the adipokines, leptin (LEP) and adiponectin (ADIPOQ), and their receptors (LEPR, ADIPOR1, ADIPOR2)." (PMID 32046756, 2020). "Our overarching hypothesis was that higher IHC expression of LEP, LEPR, ADIPOQ, ADIPOR1, and ADIPOR2 within the breast tumor microenvironment is associated with breast cancer aggressiveness, but we generally observed the opposite." (PMID 32046756, 2020). "In addition, the expression of these receptors was analyzed in breast cancer cell lines, a higher level of LEPR was observed in breast cancer cell lines compared with other adipokine receptors, except for the PAI-1 receptors." (PMID 33371368, 2020).
breast cancer (continued). "Moreover, it has been proposed that higher LepR mRNA expression and leptin signaling genes had a more fatal impact on ER- subtypes compared with ER+ breast cancer." (PMID 33019728, 2020). "Lower LEPR IHC expression within the breast tumor microenvironment might contribute mechanistically to inter-individual variation in aggressive breast cancer clinicopathology, particularly ER-negative status and triple-negative subtype." (PMID 32046756, 2020). "In contrast to our findings, several studies examining LEPR expression in breast cancer did not report significant associations of lower LEPR IHC expression with tumor features indicative of more aggressive phenotype." (PMID 32046756, 2020). "Finally, increased CXCR4 expression was accompanied by high leptin receptor expression in bone metastatic tissues from breast cancer patients." (PMID 32836215, 2020). "The pattern of tissue distribution of KHDRBS1, leptin, and LEPR in bone metastases from breast cancer is unknown." (PMID 33213024, 2020). "Leptin and the leptin receptor ObR are overexpressed in breast cancer." (PMID 33006013, 2020). "Distant leptin-derived metastatic in breast cancer is associated with 34% in the leptin receptor-positive patients, but none in the leptin receptor-negative patients." (PMID 31398937, 2019). "Despite of the elevated serum level of leptin, LepR-deficient mice (db/db) failed to develop breast cancer in an oncogene-induced rodent model (MMTV-TGF-alpha mice)." (PMID 30013512, 2018). "However, the pro-tumor effects of leptin depend on its receptor LepR, which is expressed in various tumors, including breast cancer, prostate cancer, and colon cancer." (PMID 30013512, 2018). "On the other hand, the LEPR Q223R polymorphism, involved in receptor functionality, was shown to decrease the risk of developing breast cancer in Asian women but not in Caucasian women." (PMID 30404206, 2018). "The use of leptin receptor antagonists has been well studied in breast cancer." (PMID 28861689, 2017). "First, we evaluated whether GW4064 treatment may affect the expression of leptin receptor (ObR) in breast cancer cells." (PMID 26899873, 2016). "Furthermore, blocking leptin signaling by using a full leptin receptor antagonist significantly reduced mammosphere formation in breast cancer cell lines and patient-derived samples." (PMID 26556856, 2016). "In this context, we demonstrated that CAFs, the principal cellular component of the stroma, express leptin receptor and secrete leptin, which sustains a short autocrine loop and is able to target tumor epithelial cells enhancing breast cancer cell growth and invasiveness." (PMID 26899873, 2016). "Genetically obese leptin-deficient Lepob/ob and leptin receptor-deficient Leprdb/db mice do not develop mammary tumours which provide evidence that leptin and its receptor are involved in breast tumourigenesis 11,12." (PMID 25721149, 2015). "Overall, our data demonstrate that LDFI may represent a novel leptin receptor antagonist able to reduce breast cancer progression both in vitro and in vivo, suggesting its potential use in the treatment of breast cancer, especially in obese women." (PMID 25721149, 2015). "This supports previous work demonstrating that adipose tissue from viscerally obese EAC patients induces expression of key glycolytic genes in EAC cells and a study in breast cancer, which demonstrated that leptin receptor-mediated signalling was required to support aerobic glycolysis." (PMID 25471892, 2014). "Similarly, in human primary breast cancers, leptin receptor expression is positively correlated with tumor size and ER expression." (PMID 25505738, 2014). "Indeed, ObRb, the long form of the leptin receptor stimulates proliferative and anti-apoptotic pathways, and both leptin and leptin receptors are overexpressed in human primary and metastatic breast cancer cells." (PMID 23964270, 2013).
breast cancer (continued). "In addition, AZGP1 expression is correlated positively to leptin receptor and negatively to adiponectin receptor and estrogen receptor in breast cancer tissue." (PMID 22625427, 2012). "We tested if HER2 and the leptin receptor (ObR) can be coexpressed in breast cancer cell models, whether these two receptors can physically interact, and whether leptin can transactivate HER2." (PMID 18945363, 2008). "Additionally, the leptin receptor was identified in breast cancer cell lines and in human breast cancer tissues." (PMID 18162139, 2007). "The fact that the leptin receptor was identified in human breast tumors and in human breast cancer cell lines and that the addition of leptin to breast cancer cell lines increased cell proliferation further supported the involvement of leptin in mammary tumorigenesis." (PMID 18162139, 2007). "In addition, five SNPs in three genes (ADIPOQ rs182052, rs822391 and rs7649121, CARTPT rs3846659, and LEPR rs12059300) had an effect modification on the association between IGFBP-3 serum concentration and breast cancer risk (Pinteraction < 0.05, adjusted Pinteraction < 0.20)." (PMID 35115550, 2022). "However, other studies of SNPs in EB7H3 have identified associations with C-reactive protein (CRP) levels and plasma leptin levels in women, soluble leptin receptor levels, E. histolytica infection in children, luminal A breast cancer, tolerance for exercise intensity, and exercise participation." (PMID 34421692, 2021). "Our findings thus support the previous observations on the association of excessive leptin in breast cancer progression and reveal a novel, co-operative action of the leptin receptor and mechanosensitive Ca2+ channels, which could favor the development of invasive breast cancer." (PMID 33490070, 2020). "In addition, LepR was highly expressed in breast cancer, lung cancer and colorectal carcinoma." (PMID 30013512, 2018). "Given that leptin receptor antagonists effectively inhibit breast cancer in mouse models, it is promising that utilizing a synthetic analog or monoclonal antibody as a leptin receptor antagonist may become a new strategy for the treatment for pancreatic cancer." (PMID 25948792, 2015). "Moreover, results from animal studies suggested that leptin receptor antagonists might be a new option for breast cancer treatment." (PMID 23826274, 2013). "Compared to women with the LEPR Gln223Gln genotype, those harboring the heterozygous LEPR Gln223Arg genotype (OR = 1.2, 95% CI 0.8–2.0, p = 0.42) and the homozygous mutant LEPR Arg223Arg genotype (OR = 1.5, 95% CI 0.8–2.6, p = 0.16) had no significant increased risk of breast cancer." (PMID 19017403, 2008). "Lack of oncogene-induced mammary tumors in genetically obese mice, leptin-deficient (ob/ob) mice or leptin-receptor-deficient (db/db) mice have also been discussed in light of this hypothesis." (PMID 17010200, 2006). "Consistent with these cellular findings, EMT scores derived from data on breast cancer patients exhibited a robust positive correlation with LEP and LEPR expression levels (p < 0.0001)." (PMID 41562922, 2026). "They showed that practically all breast cancer samples studied co-expressed the two main leptin receptor isoforms; long form leptin receptor (OBR-L) and short form leptin receptor (OBR-S)." (PMID 36556428, 2022). "Leptin receptor overlapping transcript (LEPROT) is reported to be involved in metabolism regulation and energy balance as well as molecular signaling of breast cancer and osteosarcoma." (PMID 34804118, 2021). "We used immunohistochemistry (IHC) to assess LEP, LEPR, ADIPOQ, ADIPOR1, and ADIPOR2 expression in breast tumor tissue microarrays among a sample of 720 women recently diagnosed with breast cancer (540 of whom self-identified as Black)." (PMID 32046756, 2020). "Here, we considered bone metastasis derived from breast carcinoma to investigate the expression in bone metastasis of biomarkers KHDRBS1, leptin, LEPR, and adiponectin." (PMID 33213024, 2020).
breast cancer (continued). "Targeting leptin signaling, by a selective leptin receptor antagonist the peptide LDFI (Leu-Asp-Phe-Ile), abrogated leptin effects on Tsg101 expression and on exosome secretion in breast cancer cells." (PMID 31336913, 2019). "Accordingly, when leptin activity was inhibited by using the full leptin receptor antagonist, the peptide LDFI, both Tsg101 expression and the amount of exosomes released by leptin-treated breast cancer cells were reduced." (PMID 31336913, 2019). "In MCF-7 and SKBR3 breast cancer cells, pre-treatment with a LDFI-leptin receptor antagonist abrogated the leptin activation of Jak2, Stat3, Akt and ERK1/2 proteins." (PMID 27480179, 2016). "Human primary and secondary breast cancer tissues were analysed for SK1 and leptin receptor expression using quantitative real-time polymerase chain reaction (qRT-PCR) assay." (PMID 25482303, 2014). "It has in fact been shown in MCF7, MDA-231 and MDA-468 breast cancer cells that treatment with leptin can phosphorylate IGF1R and activate downstream signaling while treatment with IGF1 phosphorylates leptin receptor and activates downstream signaling." (PMID 24260287, 2013). "Although the significant association between LEP, LEPR and ADIPOQ genes and breast cancer risk, we did not notice remarkable differences in circulating leptin levels across genotypes of their genetic alterations." (PMID 37274250, 2023). "Particularly, it has been found that the absence of the leptin receptor reduced the recruitment of macrophages and inhibited breast cancer growth and progression." (PMID 37509120, 2023). "Indeed, in a study conducted on 87 breast cancer patients treated with neoadjuvant chemotherapy, LEP and LEPR overexpression, were found in patients with higher levels of tumor-infiltrating lymphocytes (TILs)." (PMID 36291602, 2022). "Novel therapeutic strategies, such as LEP or LEPR antagonist, are not currently under development, although they would represent a promising step toward a more personalized treatment approach for breast cancer patients." (PMID 36291602, 2022). "The expression pattern of LEPR and LEPROT in breast cancer tissues was analyzed using TCGA data." (PMID 35223490, 2022). "Several single-nucleotide polymorphisms (SNPs) of LEP and LEPR were found correlated with breast cancer risk, including LEP-2548G/A (rs7799039), LEPR K109R (rs1137100), and LEPR Q223R (rs1137101), but the results are not exactly consistent." (PMID 35223490, 2022). "The peptide LDFI (Leu-Asp-Phe-Ile), a selective LEPR antagonist, was developed based on leptin binding site I and demonstrated to inhibit the growth and motility of both ER-positive MCF-7 and ER-negative SKBR3 breast cancer cell lines." (PMID 36291602, 2022). "Pooled data showed that PON1 rs662 and rs854560 polymorphisms were associated with risk of breast cancer in overall population, but not LEP rs7799039 and LEPR rs1137101." (PMID 34452542, 2021). "Leptin–LEPR signaling also cooperatively functions with other multiple signaling pathways, such as EGFR, Notch, IL-1, and the estrogen receptor, to enhance the proliferation, migration, invasion, and self-renewal activity of breast cancer stem cells." (PMID 34063828, 2021). "The leptin/LEPR/KHDRBS1 axis, whose components have been studied in breast cancer, may also be expressed in metastatic tissue and contribute to colonization." (PMID 33213024, 2020). "Interestingly, high expression of PAI-1 and LEPR was accompanied by the highest hazard ratio for OS and RFS of breast cancer among all the combinations of PAI-1 and adipokine receptor." (PMID 33371368, 2020). "Besides, the leptin (LEP) level was significantly positively correlated with LEPR and PAI-1 levels in breast cancer tissues via the TCGA dataset." (PMID 33371368, 2020).